MMP9 (matrix metallopeptidase 9)
Diseases named in the same sentence as MMP9 in open-access papers (continued):
Sharing a sentence is not in itself a finding about the gene and the disease.
viral infection (continued). "Targeted analysis of MMP9 (matrix metallopeptidase 9), PADI4 (peptidyl arginine deiminase 4) and LTF (lactotransferrin) showed these to be elevated in MIS-C and bacterial infection in comparison with viral infection and KD." (PMID 39300098, 2024). "In the early stage of viral infection, MMP-9 production is stimulated by inflammatory cells, especially neutrophils, and depletion of neutrophils can reduce MMP-9 activation." (PMID 32477330, 2020). "The viral infection rates of brain tissues and viral genomic copies in EGFP-CA16 + MMP9 monkeys were the highest, followed by those in EGFP-CA16 monkeys, and they were the lowest in EGFP-CA16 + TIMP-1 monkeys." (PMID 30228270, 2018). "We found that neutrophils were able to respond, by means of CXCL8, NE and MMP‐9 release, to a variety of TLR agonists that mimic viral infections." (PMID 26477783, 2016). "Notably, AKT1, FOXO1, and MMP9 were enriched in the RIG-I-like receptor and Toll-like receptor pathways, which are crucial for innate immune responses against viral infections." (PMID 40574839, 2025). "And under CypA inhibitor (CsA, an inhibitor of CypA has been commonly and widely used in a lot of fields, such as virus infection, inflammation, metabolism, and cancer) treatment, the protein expression of CD147 and MMP-9 both decreased in LPS-stimulated RAW264.7 cells." (PMID 30949512, 2019). "Genes typically associated with bacterial, but not viral infection, such as il8 (cxcl8a), tnfa, il22, were indeed not induced by SINV alone but were induced by Shigella, while mmp9 was also induced by SINV, as previously observed with CHIKV." (PMID 29881380, 2018). "In AE-COPD the gelatinolytic activity of MMP-2 was increased and furthermore, MMP-9 activation was significantly up-regulated irrespective of lung function, bacterial or viral infections and smoking." (PMID 26126526, 2015). "Initial BioPlex screens and RT-PCR did not detect MMP9 after virus infection (data not shown)." (PMID 30442185, 2018). "Both wt and E1A mutant virus infection of mice led to similar increases in the activity of two matrix metalloproteinases known to correlate with BBB disruption, MMP2 and MMP9, while causing no increase in the steady-state expression of MMP2 or MMP9 mRNA." (PMID 27303733, 2016). "Although the TGFβ2 factor, recently recognized as a key factor in fibrosis induction, did not result upregulated by virus infection in HUVECs, other factors belonging to TGFβ superfamily were promoted in particular by HHV-6A, including GREM1 and INHBE, IL-4, IL-5, TNF, and MMP9." (PMID 31878218, 2019).
chronic kidney disease (35 papers, 2012 to 2025). Impairment of the renal function secondary to chronic kidney damage persisting for three or more months. "The role of matrix metalloproteinase 9 (MMP-9) in the pathophysiology of chronic kidney disease (CKD), which is associated with a nearly two-fold greater risk for urinary calculi compared to people without CKD, has been demonstrated." (PMID 37332754, 2023). "In chronic kidney disease, MMP9 activity is associated with resistant albuminuria." (PMID 39086962, 2022). "Moreover, it has been suggested that elevated levels of MMP-2 and decreased concentration of MMP-9 are associated with the development of chronic kidney disease." (PMID 26843213, 2016). "Background and objectives: Data concerning the concentration of matrix metalloproteinase-9 (MMP-9) and its functional polymorphisms in chronic kidney diseases (CKD) are conflicting." (PMID 27829825, 2016). "It has been found that MMP-2 and MMP-9 expressions are dysregulated in both acute and chronic kidney diseases." (PMID 37287620, 2023). "MMP9 has been recognized in chronic kidney diseases and is an important indicator for the early diagnosis of HSPN." (PMID 36389115, 2022). "Several studies have exhibited the crucial role of MMP9 in angiogenesis, leading to chronic kidney disease (CKD)." (PMID 34607974, 2021). "MMP-9 is also known to be involved in various inflammatory and chronic kidney diseases, especially in obstructive nephropathy." (PMID 28235038, 2017). "As a key enzyme involved in ECM degradation, MMP-9 has been observed to be differentially expressed in acute and chronic renal disease models." (PMID 24396399, 2014). "Both MMP-2 and MMP-9 are highly expressed in the tubular compartment in animal models with chronic kidney disease, and they were also found in the serum of patients with chronic kidney disease." (PMID 24719498, 2014). "Metalloproteinase-2 (MMP-2) and metalloproteinase-9 (MMP-9) are members of the gelatinase family and were demonstrated in animal models and in vitro systems as important mechanisms of fibrosis in progressive chronic kidney disease." (PMID 24719498, 2014). "An angiotensin converting enzyme inhibitor, ramipril, had been investigated to find the contribution of MMP-9 in the process of glomeruloscelrosis and chronic renal disease in hypertensive rats." (PMID 23110201, 2012). "Therefore, we created AV fistulas (end-to-side anastomosis) in wild-type (WT) and MMP-9 knockout mice with chronic kidney disease to further clarify this." (PMID 34064140, 2021). "The present study aimed to evaluate the levels of MMP-9in children with end stage renal diseases (ESRD) on hemodialysis (HD) and to explore its association with MMP-9 polymorphism and vitamin D levels as an important risk factors for cardiovascular diseases (CVD)." (PMID 27829825, 2016). "In models of chronic kidney disease, decreased MMP-9 has been shown to aid disease progression." (PMID 22315658, 2012). "During renal fibrosis which is the main pathological changes of chronic kidney disease (CKD), transcription levels of MMP-9 mRNAs increase as a result of abnormal activation and interaction of multiple cell signaling pathways." (PMID 37332754, 2023). "Because the extent of fibrosis is strongly associated with the rate of progression to end stage renal disease in ADPKD patients, this result could account for the protective role of MMP9 in the pathology, as demonstrated by improved kidney function and life expectancy." (PMID 38039285, 2023). "In our previous report, MMP-9 mRNA expression in AV fistula was upregulated in chronic kidney disease (CKD) condition and reduced after lowering indoxyl sulfate, a uremic toxin, with oral carbonaceous adsorbent." (PMID 34064140, 2021).
chronic kidney disease (continued). "The weaker correlation at T3 could therefore indicate that MMP-9′s ability to mitigate proteinuria diminishes over time as fibrotic changes become more pronounced, highlighting the shift from inflammation-driven to fibrosis-driven pathology in chronic kidney disease." (PMID 40428765, 2025). "It is known that in ALS there is a slightly higher prevalence (~10%) of chronic kidney disease (CKD), whereby persistent inflammation and oxidative stress stimulate the upregulation of MMP-9 expression by immune cells such as macrophages, as well as renal tubular epithelial cells." (PMID 41009467, 2025). "Conversely, in the progression of chronic kidney disease, the knockout of NLRP3 is accompanied by the downregulation of MMP9." (PMID 38992615, 2024). "Another rat model, in this case displaying vascular calcification in chronic kidney diseases, exhibited a raised MMP-2 and MMP-9 expression and activity upon arterial calcification." (PMID 37189419, 2023). "In the advanced stage of chronic kidney disease, the activity of MMP-2 and MMP-9 is decreased and, in this late period, the fibrosis is difficult to reverse." (PMID 32403389, 2020). "This study shows that cell proliferation, differentiation, apoptosis, migration (SRC, HRAS, HSP90AA1, CDK2), and ameliorating chronic kidney disease (MAPK14, F2, LCK, MMP9) appear to play important roles in the therapeutic effect of SQW." (PMID 31275142, 2019). "Matrix metalloproteinases (MMPs), in particular MMP9 and MMP2, are up-regulated in chronic kidney diseases and they sustain fibrosis via TGF-beta pathway." (PMID 30546836, 2018). "Accumulating data have shown that MMP-9 and TIMP-1 function differentially in chronic kidney diseases (CKDs)." (PMID 24396399, 2014). "MMP-9 is initially believed to be involved in the pathogenesis of chronic kidney disease (CKD)." (PMID 23110201, 2012). "Mounting proof demonstrates that imbalanced MMP activity contributes to atherosclerotic diseased vessels in patients with renal failure, especially MMP-9 which is correlated with atherosclerosis in non-dialytic chronic kidney disease." (PMID 27829825, 2016). "Also, MMP-2 and MMP-9 may participate in pathological remodeling of extracellular matrix (ECM) in kidney disease related to hypertension, leading to renal sclerosis and ultimately chronic kidney disease." (PMID 38791032, 2024). "Therefore, the upregulated MMP-9 in the early stage of CAN, showed in our data, might degrade extracellular matrix, which further aggravate the mononuclear cells infiltration, and lead to tubulointerstitial fibrosis and chronic renal failure eventually." (PMID 23351884, 2013).
esophageal squamous cell carcinoma (35 papers, 2013 to 2025). Esophageal squamous cell carcinoma (ESCC) is a type of esophageal carcinoma (EC) that can affect any part of the esophagus, but is usually located in the upper or middle third. "The quantity of M2 macrophages in tumor stroma was positively associated with microvessel density and the expression of MMP9, and as an independent poorly prognostic factor for overall survival time of Kazakh esophageal squamous cell carcinoma." (PMID 28423526, 2017). "According to the literature, the expression and the activity of various matrix metalloproteinases (MMPs), including MMP9, were found to be upregulated in more than 60% of esophageal squamous cell carcinoma cases." (PMID 33572115, 2021). "PTK7 activates AP-1 and NF-κB signaling and upregulates matrix metalloproteinase-9 (MMP9) which results in increasing invasive properties of esophageal squamous cell carcinoma cells." (PMID 34367983, 2021). "Stratified analysis of correlation between clinicopathologic features and VEGF-C and MMP-9 expression in Kazakh esophageal squamous cell carcinoma (ESCC) tissues." (PMID 31824776, 2019). "For example, the MMP-9/NGAL complex activity has been positively correlated with the depth of invasion of esophageal squamous cell carcinoma." (PMID 26663949, 2015). "MMP2 and MMP9 are two important members of the MMP family, and overexpression of MMP2 and MMP9 has been confirmed to associate with a variety of malignancies that contain esophageal squamous cell carcinomas." (PMID 24885858, 2014). "However, MMP2 and MMP9 are inhibited by miR-34a-5p in esophageal squamous cell carcinoma." (PMID 30696040, 2019). "Correlation between VEGF-C/MMP-9 expression and clinicopathologic parameters in Kazakh esophageal squamous cell carcinoma (ESCC) tissues." (PMID 31824776, 2019). "PLAU also promoted Esophageal squamous cell carcinoma proliferation and colony formation through MAPK pathway, and promoted migration through up-regulation of Slug and MMP9, leading to an increase in fibrosis." (PMID 38575860, 2024). "In esophageal squamous cell carcinoma, pharmacological inhibition of PAK1 reduces cancer cell migration and invasion as well as matrix metalloproteinase (MMP)-2 and MMP-9 expression." (PMID 38188678, 2023). "The LCN2/LOXL2/MMP9 ternary complex promoted migration and invasion of oesophageal squamous cell carcinoma (ESCC) cells, as well as tumour growth and malignant progression in vivo, while the iron chelator deferoxamine mesylate (DFOM) inhibited ESCC tumour growth." (PMID 37753805, 2023). "GPx3 can also suppress the expression of matrix metalloproteinase 9 (MMP-9) by deactivating the focal adhesion kinase (FAK)-AKT pathway, leading to decreased invasiveness of esophageal squamous cell carcinoma cells." (PMID 32781581, 2020). "In esophageal squamous cell carcinoma, LCN2 expression is modulated by the transcription factors TCF7L2 and EGR1, leading to increased activity of matrix metalloproteinase-9 (MMP-9), rearrangement of cytoskeletal F-actin, as well as increased invasiveness and migration through the MEK/ERK pathway." (PMID 34062746, 2021). "CypA/MMP9 signal pathway and up-regulation of USP9X may be attributed to the malignant transformation of esophageal squamous cell carcinoma (ESCC)." (PMID 25047112, 2014). "The HMGA2 protein is a non-histone chromatin factor involved in DNA repair, aggressiveness of esophageal squamous cell carcinoma, epithelial-to-mesenchymal transition (EMT) process, and the up-regulation of EMT-related genes such as TGF-beta, SNAIL1, SLUG, MMP2, and MMP9 in RMS patients." (PMID 36139434, 2022). "Also, the overexpression of miR-34a significantly inhibited the migratory and invasive potential of esophageal squamous cell carcinoma (ESCC) cells via inhibition of FNDC3B (Fibronectin Type III Domain Containing 3B), MMP2 (matrix metalloproteinase-2) and MMP9 expression levels." (PMID 29036883, 2017).
Granuloma (35 papers, 2009 to 2026). A compact, organized collection of mature mononuclear phagocytes, which may be but is not necessarily accompanied by accessory features such as necrosis. "MMP-9 has also been detected in granulomas in human brain biopsies and has been linked to BBB breakdown." (PMID 37196131, 2024). "Our data found extensive up-regulation of MMP-9 in various tuberculosis-associated granulomas and demonstrated the significance of MMP-9 in granulomatous fibrosis." (PMID 38235425, 2023). "Considering the liver damage caused by schistosomal infection, it is possible that MMP9 also can attract immature hematopoietic cells to cellular proliferation regions, especially in the periphery of granulomas." (PMID 36091027, 2022). "MMP-9 is a metalloprotease that has been associated with macrophage recruitment and wound healing, and the formation of well-defined and stable granuloma in both murine and zebrafish models of mycobacterial infection." (PMID 30625198, 2019). "Mycobacteria are also able to exploit the host’s resources for their own benefit, for example by inducing the expression of matrix metalloproteinase-9 (MMP9) in the host for the recruitment of macrophages or by initiating granuloma-associated angiogenesis." (PMID 28742838, 2017). "In the intraperitoneal model of PCM using WT and iNOS−/− mice, NO production was associated with increased MMP9 activity and the loose organization of granulomas developed by WT mice." (PMID 23936574, 2013). "During mycobacteria infection, MMP-9 induction has been implicated in cells recruitment, representing as an obligatory step in the formation of granuloma." (PMID 19290049, 2009). "Furthermore, matrix metalloproteinases (MMPs) associated with ultraviolet radiation, especially MMP-9, are significantly upregulated in GR lesions, implicating them in granuloma formation and tissue remodeling." (PMID 40918550, 2025). "MMP-9 has been linked to the intensity of the tuberculosis and the development of TB granulomas." (PMID 34944659, 2021). "In summary, the results obtained in the present study demonstrated that IL-17A and MMP-9 were expressed in the granuloma of different mycetoma causative agents and that the expression of IL-17A was more extensively in larger leasions and lesions with a longer disease duration." (PMID 31295246, 2019). "Beyond its Th17-suppressive and skin-barrier-restorative activities, tapinarof directly dampens LL-37-induced mast-cell degranulation, down-regulating chymase-1, tryptase-β, MMP-9, TNF-α and IL-6—mediators implicated in granuloma formation." (PMID 41451029, 2026). "In-vitro data further show that tapinarof attenuates LL-37–driven mast-cell degranulation and decreases MMP-9, TNF-α, and IL-6, all implicated in granuloma formation and dermal remodeling." (PMID 41451029, 2026). "Its expression is stronger in later-stage granulomas with less lymphocyte infiltration, suggesting that MMP-9 promotes granulomatous fibrosis in the chronic sarcoidosis stage." (PMID 41463010, 2025). "For MMP9 (m/z = 959.404) spatial distribution in bovine and porcine granulomas, epithelioid macrophages, multinucleated giant cells, and neutrophils and fibroblasts from the periphery of granulomas were immunolabeled in both species." (PMID 39021575, 2024). "We have found that in lesion samples of sarcoidosis with abundant lymphocytes, the histiocytes expressed less MMP-9, while in granulomas surrounded by peripheral fibrous tissue, fewer lymphocytes were observed and the expression of MMP-9 was stronger." (PMID 36959923, 2023). "Inside the granulomas, at 50 and 60 dpi, the MMP9-positive neutrophils were located along the peripheral zone." (PMID 36091027, 2022). "It has already been shown that MMP-9 is overexpressed by monocytic cells in granulomas from tuberculosis cases and the TNF- α blockade decreased the expression of MMP-9 by 50% revealing that TNF- α is a key cytokine in monocyte-derived MMP-9 secretion." (PMID 35041718, 2022).